MGMT (O-6-methylguanine-DNA methyltransferase)
Diseases named in the same sentence as MGMT in open-access papers (continued):
Sharing a sentence is not in itself a finding about the gene and the disease.
malignant glioma (77 papers, 2003 to 2025). A grade III or grade IV glioma arising from the central nervous system. "Methylation of the MGMT gene promoter occurs in 35–45% of malignant gliomas, and it has been associated with decreased expression of O6-methylguanine-DNA methyltransferase (MGMT), an enzyme that reduces DNA damage." (PMID 39518074, 2024). "Taking the prognosis studies of malignant glioma for instance, we have found that MGMT promoter methylation was associated with worse OS among Asians, whereas it was associated with longer OS among Caucasians." (PMID 28042954, 2017). "There are at least a few studies on malignant gliomas which corroborate that MGMT-immunoreactivity is associated with survival and/or response to alkylating substances." (PMID 19274096, 2009). "Additionally, we examined the influence of molecular markers for prognostic significance in malignant glioma, including MGMT promotor methylation status, IDH-1/2 mutation and loss of ATRX on overall survival." (PMID 35183162, 2022). "In addition to chromosomal changes, mostly chromosome 1p/19q deletion, prominent genetic and epigenetic alterations like IDH mutations and MGMT gene promoter methylation, respectively, have been found in malignant gliomas." (PMID 33552543, 2020). "The aim of this study is to investigate whether the therapeutic efficacy of bevacizumab (BEV) in the treatment of high-grade glioma (HGG) is associated with the methylation status of O6-methylguanine-DNA methyltransferase (MGMT) on the basis of excluding the interference from chemotherapy drugs." (PMID 40963873, 2025). "These biomarkers such as IDH gene mutation and MGMT promoter methylation status help to predict prognosis and could predict response to specific chemotherapies, thus holding promise for the safe and specific treatment of malignant glioma." (PMID 33552543, 2020). "Quantifying O6-methylguanine-DNA methyltransferase (MGMT) promoter methylation plays an essential role in assessing the potential efficacy of alkylating agents in the chemotherapy of malignant gliomas." (PMID 33917711, 2021). "Malignant gliomas often show resistance to alkylating drugs due to the increased expression of MGMT, which remains a significant obstacle to clinical treatment." (PMID 33614641, 2021). "In malignant gliomas, the combination of IDH1 mutations and MGMT methylation status is more predictive of survival than either IDH1 or MGMT alone." (PMID 34638714, 2021). "The impact on survival of complete resection (CR) in patients with malignant glioma and MGMT promoter methylation on adjuvant therapy strategies has been proven in the past." (PMID 34185258, 2021). "The current study was designed to analyze the prognostic implications of IDH1/2 gene alterations and MGMT gene methylation for their individual as well as cumulative impact on outcome of malignant glioma patients with diverse histologies." (PMID 33552543, 2020). "Patients with newly diagnosed malignant gliomas will have their tumor tissue samples submitted for the analysis of the status of O-6-methylguanine-DNA methyltransferase (MGMT) promoter methylation." (PMID 30786916, 2019). "O6-methylguanine-DNA methyltransferase (MGMT), which is a DNA repair protein, also remains a barrier preventing the successful treatment of patients with malignant glioma." (PMID 30645699, 2019). "The quantum of expression in malignant gliomas varied to a great extent wherein tumors with intact MGMT showed higher levels of expression than adjacent normal tissue." (PMID 29712977, 2018). "Methylation of the MGMT promoter is found in 35%–45% of malignant gliomas (WHO grades III and IV) and in about 80% of WHO grade II gliomas." (PMID 29712977, 2018). "This study investigated methylation status of MGMT gene along with in situ protein expression in malignant glioma patients of different histological types to evaluate the associated clinical outcome vis-a-vis use of alkylating drugs and radiotherapy." (PMID 29712977, 2018).
malignant glioma (continued). "Because of this reason determination of the methylation pattern of the MGMT gene becomes mandatory in patients with malignant glioma." (PMID 29712977, 2018). "This study included 63 confirmed cases of malignant glioma patients which were analyzed for MGMT gene methylation and its protein expression to observe the impact of alkylating chemotherapeutic agent Temozolomide on the OS and PFS of the patients." (PMID 29712977, 2018). "On the other hand, methylation of the O6-methylguanine-DNA methyltransferase (MGMT) of the MGMT promoter of malignant glioma appears to be a useful predictor of the responsiveness to alkylating agents that reverse epigenetic alterations." (PMID 29686400, 2018). "Accumulating evidence strongly suggests the role of O6-methylguanine-DNA methyltransferase (MGMT) expression in the acquired resistance to TMZ in malignant glioma and acute leukemia cells." (PMID 28279189, 2017). "Previous study of pediatric malignant gliomas showed improved progression-free survival in patients with low tumor levels of MGMT receiving alkylation-based chemotherapy (97 out of 109 patients)." (PMID 26933822, 2016). "It was demonstrated that in malignant gliomas of WHO grades III/IV with the IDH1 mutation, MGMT promoter methylation was associated with prolonged Progression-free survival (PFS) with chemotherapy ± radiation therapy (RT) or RT-only groups." (PMID 27834917, 2016). "MGMT, a DNA repair enzyme, plays a crucial role in mediating resistance to alkylating agents in various tumors, especially malignant gliomas." (PMID 27566252, 2016). "MGMT is a DNA repair protein that counteracts the effect of TMZ which is used for malignant glioma standard treatment." (PMID 25027022, 2014). "We evaluated the significance of these markers, that is, 1p/19q co-deletion, MGMT promoter methylation, and IDH1 mutations, in malignant glioma." (PMID 24160898, 2013). "In this study, we focused on 1p/19 co-deletion, MGMT promoter methylation status, and IDH1 mutations in patients with malignant glioma." (PMID 24160898, 2013). "MGMT, a DNA repair enzyme, is known to induce resistance to chemotherapy in some patients with malignant gliomas." (PMID 24160898, 2013). "The alkylating agent temozolomide (TMZ) has been shown to improve the overall survival in patients with malignant gliomas, especially in tumors with methylated promoter of the O6-methylguanine-DNA-methyltransferase (MGMT) gene." (PMID 23704990, 2013). "MGMT hypermethylation have been proven to be useful predictors of prognosis and responsiveness in gastric cancers and malignant gliomas." (PMID 23573237, 2013). "Due to the prognostic and predictive role of the MGMT promoter status for patients suffering from malignant glioma, promoter methylation of this gene is commonly assessed both in clinical trials and routine diagnostics." (PMID 22428052, 2012). "It has been shown that TMZ was effective in malignant glioma with low mRNA and/or protein levels of MGMT." (PMID 23091742, 2012). "Assessment of the methylation status of the O6-methylguanine-DNA methyltransferase (MGMT) gene promoter in malignant glioma has become one of the most requested molecular assays in clinical neuro-oncology." (PMID 22428052, 2012). "Recently published results of trials on elderly patients with malignant gliomas have revived the call for routine MGMT testing for clinical decision making." (PMID 23083460, 2012). "The relevance of MGMT status as a potential prognostic or predictive factor in malignant glioma patients is supported by a number of independent studies." (PMID 21269507, 2011). "Multiple studies have now validated the clinical importance of MGMT expression as a marker for resistance to temozolomide in the treatment of malignant glioma." (PMID 20628383, 2010).
malignant glioma (continued). "The O6-methylguanine-methyltransferase (MGMT) promoter methylation status is a predictive parameter for the response of malignant gliomas to alkylating agents such as temozolomide." (PMID 19274096, 2009). "In fact, tumors have long been noted to be heterogeneous in MGMT expression, and approximately half of malignant gliomas expressed MGMT." (PMID 17547775, 2007). "We hypothesized that CRISPR-mediated methylation of the MGMT promoter region may serve as a therapeutic strategy to enhance chemosensitivity in malignant glioma by silencing MGMT expression." (PMID 38224404, 2024). "MGMT promoter methylation and subsequent MGMT gene inactivation is common in malignant gliomas." (PMID 37454191, 2023). "The present study was aimed to investigate the prognostic scope of MGMT by evaluating both its promoter methylation status and protein expression in a series of primary malignant glioma patients with varied histologies treated with alkylating agent, Temozolomide and radiotherpay." (PMID 29712977, 2018). "MGMT promoter gene methylation followed by its subsequent protein inactivation has been substantiated to modulate response of chemotherapeutic drugs like alkylating agents (Temozolomide) commonly used in malignant gliomas." (PMID 29712977, 2018). "MGMT gene has been successfully substantiated in many investigations to be applied as a therapeutic target when downregulated to increase the chemosensitivity of malignant gliomas to alkylating drugs (TMZ)." (PMID 29712977, 2018). "Since therapeutic response of malignant glioma to TMZ is known to be highly correlated with MGMT promoter methylation and a subsequent decrease in MGMT protein expression, we performed Western blotting of MGMT protein in 19 out 20 cell cultures tested in our initial drug screening." (PMID 25886061, 2015). "Genomic biomarkers of malignant glioma include isocitrate dehydrogenase 1/2 (IDH1/2) mutations, O-6-methylguanine-DNA methyltransferase (MGMT) promoter methylation status and 1p19q co-deletion, and these markers provide information on prognosis and response to treatment." (PMID 25897422, 2015). "Of the 267 malignant glioma patients, 134 exhibited MGMT promoter methylation (49.4%)." (PMID 24160898, 2013). "Our study also showed significantly greater MGMT methylation in malignant glioma patients with IDH1 mutations than in those without (P < 0.0001)." (PMID 24160898, 2013). "MGMT has been used as a therapeutic target because downregulation of MGMT may enhance the chemosensitivity of malignant gliomas to TMZ." (PMID 21829728, 2011). "Interestingly, the incidence of malignant gliomas peaks around age 40–50, which is the same age period when MGMT hypermethylation emerged in the samples of the present study." (PMID 17878930, 2007). "A recent clinical trial showed that analysis of MGMT expression could predict resistance to TMZ in malignant glioma." (PMID 14562026, 2003). "Thus, similarly as for malignant gliomas, where epigenetic silencing of the MGMT gene by promoter methylation has been shown to be of predictive value for profiting from TMZ, TMZ efficacy needs to be correlated to the MGMT promoter methylation status in individual brain metastases." (PMID 19274096, 2009). "A positive correlation between MGMT level and phosphorylated STAT3 has been reported in human malignant gliomas, which is consistent with our report." (PMID 37298405, 2023). "Our findings indicate that this regulator of epithelial-mesenchymal transition orchestrates key features of cancer stem cells in malignant glioma and identify ROBO1, OLIG2, CD133 and MGMT as novel targets of the ZEB1 pathway." (PMID 23818228, 2013). "The objective of this study is to investigate the predictive role of O6-methylguanine-DNA methyltransferase (MGMT) and isocitrate dehydrogenase (IDH) status on the efficacy of bevacizumab (BEV) in high-grade glioma (HGG), while excluding the interference of chemotherapy agents." (PMID 40927528, 2025).
malignant glioma (continued). "In summary, we show that concurrent dosing of MGMT-modified γδ T cells can improve survival outcomes in a PDX model of both classical and mesenchymal subtypes of primary high-grade gliomas over either single-agent chemotherapy and single agent γδ T cell-based therapies." (PMID 34702850, 2021). "We further suggest that the analysis of expression level of both MGMT and MPG in tumor samples after surgery or biopsy might be used to predict effectiveness of TMZ treatment in malignant glioma patients." (PMID 33335215, 2020). "Neither theprognostic/predictive impact of DNMT expression in malignant glioma nor itsassociation with MGMT promoter methylation has been analyzed sofar." (PMID 21365007, 2011). "Although MGMT promoter methylation is known to be a predictive factor for the success of using alkylating substances like TMZ in malignant gliomas, MGMT promoter methylation of brain metastases has not been explored in depth." (PMID 19274096, 2009). "A strategy that involved the pretreatment with the MGMT pseudo-substrate O6-benzylguanine (O6-BG) even if it proved effective in overcoming TMZ resistance, in a subsequent phase II trial showed a positive response in only one out of thirty-four patients with recurrent TMZ-resistant malignant glioma." (PMID 35053068, 2022). "Interestingly, ZEB1, a regulator of EMT, plays an important role in key features of cancer stem cells including the regulation of stemness and chemoresistance induction through transcriptional regulation of O-6-Methylguanine DNA Methyltransferase (MGMT) via miR-200c and c-MYB in malignant glioma." (PMID 29681949, 2018). "Although it has been reported that the postoperative first-line chemotherapy for malignant glioma, TMZ, preferentially removes GSCs expressing high levels of DNA repair protein MGMT, the drug does not inhibit self-renewal of GSCs expressing a normal level of MGMT." (PMID 23762610, 2013). "In addition, the ability of PUMA to induce apoptosis in malignant glioma cells may be independent of MGMT." (PMID 25625235, 2015). "We also demonstrated that CTSB is highly-expressed in known malignant glioma molecular phenotypes such as IDH wild-type, MGMT promoter unmethylation, 1p19q non-codeletion and mesenchymal subtype." (PMID 35277559, 2022). "Thus, in malignant glioma (grades III and IV), MGMT is completely lacking in about 20% of the tumors and epigenetically downregulated in about 40% of neoplasias, resulting in a significant decrease in MGMT repair activity." (PMID 34639014, 2021).
lung carcinoma (68 papers, 2007 to 2026). "Demethylating MGMT can enhance the repair of the damage to the DNA caused by alkylating agents, improving response to these chemotherapeutic drugs in lung cancer treatment." (PMID 40191732, 2025). "Detection of MGMT methylation in sputum and plasma has shown promise as a non-invasive biomarker for the detection of lung cancer in its early stages and risk assessment." (PMID 40191732, 2025). "The occurrence and development of various malignant tumors (such as lymphoblastoma, lung cancer, esophageal cancer) are related to MGMT protein expression loss and DNA repair disorder caused by MGMT gene promoter methylation." (PMID 34026352, 2021). "Our data indicated that multidrug resistance of lung cancer cells is partly associated with Trps1‐regulated MGMT gene transcription." (PMID 29601666, 2018). "Although the possible association between MGMT polymorphisms and lung cancer risk has been examined in several studies, most results have been inconclusive and not included information on sex difference." (PMID 24212786, 2011). "Aberrant DNA methylation is closely associated with cellular dysfunctions in lung cancer, such as DNA repair (O6 methylguanine DNA methyltransferase, MGMT), cell growth (Short State Homebox2, SHOX2), and cell cycle (cycling dependent kinase inhibitor 2A, CDKN2A)." (PMID 40666096, 2025). "Furthermore, certain methylation markers, such as DAL-1, EPHB6, HS3ST2, TMEM88 and MGMT, specifically associated with lung cancer progression and metastasis, were found to have increased methylation levels." (PMID 37506102, 2023). "The presence of MGMT promoter methylation in the sputum of smokers who have never developed cancer points to a link between promoter methylation and the risk of developing lung cancer." (PMID 37901797, 2023). "Over 10-fold inter-individual variation in MGMT activity has been observed in normal tissues, and lower MGMT activity is associated with therapy related leukemia, myelotoxicity in patients receiving temozolomide, and lung cancer risk." (PMID 30811507, 2019). "When the subgroup analyses were carried out according to tumor site, the MGMT T allele was associated with a significant increase in risk of lung cancer (TT Versus CC, P=0.027, OR =1.67, 95% CI 1.06-2.63; recessive genetic model, P=0.32, OR=1.64, 95% CI 1.04-2.58)." (PMID 24086516, 2013). "In patient datasets, lower LMO7 expression and higher MGMT expression correlate with shorter overall survival in lung cancer (Kaplan-Meier Plotter analysis, p < 0.01)." (PMID 41763308, 2026). "Seven tumor suppressor genes (CDKN2A, CDH13, MGMT, MIR137, DAPK1, RARB, and RASSF1A) consistently exhibited hypermethylation in both lung cancer and in association with smoking exposure." (PMID 42073597, 2026). "In lung cancer cell lines, these agents have been shown to demethylate and reactivate genes such as p16, MGMT, and RASSF1A, resulting in reduced cell proliferation and increased apoptosis." (PMID 40191732, 2025). "Studies have demonstrated that the methylation of genes like CDKN2A (p16), MGMT, and RASSF1A can be identified in sputum samples from high-risk individuals before clinical diagnosis of lung cancer." (PMID 40191732, 2025). "It has been shown that MGMT hypermethylation is present in a significant proportion of sputum samples from individuals who later develop lung cancer, underscoring its utility in early screening programs." (PMID 40191732, 2025). "The usefulness of methylation signatures in the ctDNA of lung cancer was demonstrated in the serum of 200 patients by identifying hypermethylated promoter regions of tumor suppressor genes (MGMT, CDKN2A, INK4A, RASSF1A, DAPK, and RARB." (PMID 36765815, 2023). "Certain methylation markers specifically associated with lung cancer progression and metastasis, such as increased methylation of DAL-1, EPHB6, HS3ST2, TMEM88 and MGMT, and decreased methylation of ELMO3, are linked to higher rates of metastasis in NSCLC." (PMID 35205708, 2022).